CFTR (CF transmembrane conductance regulator)
Diseases named in the same sentence as CFTR in open-access papers (continued):
Sharing a sentence is not in itself a finding about the gene and the disease.
infection (continued). "Thus, use of an alternate definition of infection does not substantially alter the association between predicted CFTR function and acquisition of Pa, MPa or Asp." (PMID 20932301, 2010). "In CF infants, CFTR mutation itself could produce an inflammatory milieu in the airway even in absence of pathogen infection, suggesting dysfunctional immune regulation." (PMID 19344509, 2009). "Defective cystic fibrosis transmembrane conductance regulator (CFTR) function disrupts airway hydration and mucociliary clearance, creating a microenvironment that facilitates infection, particularly with Pseudomonas aeruginosa (P." (PMID 42198683, 2026). "An additional example is infection of BALB/c mice with mouse-adapted wildtype SARS-CoV virus, in which CFTR mRNA in lung is reduced by ca 60% on day 4 after infection." (PMID 39043712, 2024). "At 12- and 24-hours post infection, TER had dramatically deteriorated in both CF (CO 56% and 75%, GE 64% and 80%, respectively) and CF+CFTR (CO 23% and 45%, GE 37% and 56%, respectively)." (PMID 37680748, 2023). "The only two subjects who successfully cleared the infection had the lowest baseline sweat chloride values and reached the lowest values after IVA, suggesting that the infection clearance could be associated at least in part to the amount of CFTR activity reached after treatment." (PMID 35406809, 2022). "To evaluate their response to infection, we monitored the epithelial integrity of the CFTR-CTL and CFTR-KD cell cultures after the apical inoculation of 103 CFU of the wild type PAO1 for 6, 16, and 24 h." (PMID 35563895, 2022). "Both immortalized and primary human bronchial epithelial cells expressing wt or F508del-CFTR along with CRISPR/Cas9 CFTR-ablated clones were infected with SARS-CoV-2 and samples were harvested before and from 24 to 72 h post-infection." (PMID 35456026, 2022). "After infection with SARS-CoV-2, the intracellular nsp14 viral mRNA level was increased, and this level was significantly higher in Calu-3-CFTR-KD than -CFTR-WT cells and was even more notably elevated when the cells were pre-stimulated with flagellin." (PMID 34950129, 2021). "Despite investigating this in depth, there is no clear explanation for this clustering based on batch effects, age, CFTR genotype, bronchoalveolar lavage (BAL) cell counts, BAL IL-8 or neutrophil elastase levels, infection status or antibiotic treatment." (PMID 31980676, 2020). "To determine if CFTR KO alters macrophage cytokine production, we measured production of 5 cytokines (IL-8, IL-1β, IL-6, IL-10, and TNF-α) at baseline and in response to infection with B. cenocepacia." (PMID 32973772, 2020). "Genetic and acquired loss-of-function defect of the cystic fibrosis transmembrane conductance regulator (CFTR) compromise airway surface liquid homeostasis and mucociliary clearance (MCC), culminating in recurrent lung inflammation/infection." (PMID 31481727, 2019). "Increased infection and replication will increase the HIV Tat burden in the airway that, with CS additively suppresses CFTR biogenesis and function." (PMID 29789655, 2018). "To test the effects of overexpression of CFTR in hepatocytes on the expression of autophagy-related proteins p62, BECN1, LC3, and Atg12, we detected their expression after infection." (PMID 29415998, 2018). "All together, these results suggest that the gut microbiota in children with CF is intrinsically linked to CFTR impairment, regardless of age, and with dysbiosis uninduced by pancreatic function, diet and in part related to oral antibiotic therapy or lung colonization/infection." (PMID 30521551, 2018). "More severe CF transmembrane conductance regulator (CFTR) mutations are associated with poorer clinical outcomes; however, identification of exogenous factors that contribute to the inflammatory process and susceptibility to infection may provide an opportunity for intervention." (PMID 28750627, 2017).
infection (continued). "We first report that exoproducts from either the laboratory PAO1 strain or a clinical ≪Early≫ isolate (from an early stage of infection) altered CFTR expression, localization and function in AEC expressing wt-CFTR." (PMID 29177135, 2017). "In contrast, the resistance of F508del CFTR transduced cells infected with RSV rapidly decreased within 24 h and over several days post-infection (−236.62 Ωcm2 ± 27.96 mean ± SEM Ωcm2 per day; p < 0.0001)." (PMID 24056672, 2013). "In contrast, F508del CFTR cells have the highest RSV titer on day 2, followed by decreasing viral titers on days 4 and 6 post-infection." (PMID 24056672, 2013). "On day 4 and 6 post infection, measured RSV titers in F508del CFTR cells were 142-fold and 25-fold higher compared to viral load measured in wt CFTR monolayers (p = 0.000005 and 0.0002, respectively)." (PMID 24056672, 2013). "We did not assess CFTR modulators in our murine infection model as despite showing a CF hyperinflammatory phenotype, in the context of this being a CFTR knockout, it lacks murine CFTR for the modulators to target." (PMID 39903773, 2025). "Defective CFTR function indeed induces the expression of pro‐inflammatory mediators also in absence of any infection, with CF cells showing constitutive NF‐κB hyperactivation and ERK upregulation." (PMID 41070403, 2025). "Although uptake of fungal conidia was not impaired in CFTR-/- macrophages, we found that fungal killing was impaired at 6 hours post-infection." (PMID 39903773, 2025). "ENaC, CFTR, and Na,K-ATPase dysfunction were found to be exclusive to IAV-infected cells rather than uninfected cells, wherein CFTR dysfunction persisted even after the period of infection." (PMID 38256480, 2024). "While it wasoriginally proposed that altered CFTR function might affect host ACE2receptor presentation and viral entry, addition of IOWH-032 at differentstages of infection suggested that the drug affects the intracellularphases of viral replication." (PMID 38980755, 2024). "Additionally, the use of CFTR modulators such as ETI exhibits promising effects against Af colonization and infection, as evidenced by various clinical and basic science studies, thereby eliminating the initial trigger for disease formation." (PMID 39330416, 2024). "The ΔF BHK cells showed upregulated oxidative phosphorylation, suggesting that in the absence of any infection or inflammatory stimuli, CFTR dysfunction alone influences the metabolic trajectory of a particular cell type." (PMID 39498005, 2024). "Without CFTR, airway barrier mechanisms are impaired, allowing for chronic, recurrent infections that result in airway remodeling and deterioration of lung structure and function." (PMID 39439894, 2024). "By contrast, the second states that the exacerbated inflammation found in CF is caused by microbial (Pseudomonas aeruginosa (P.a), Burkholderia cepacia...) infections which thrive because of lack of CFTR or following mucus accumulation in the lung mucosa." (PMID 38469306, 2024). "In response to infection with conidia or germlings, epithelial barrier function degraded time-dependently (based on ZO-1 immunofluorescence and TER) with a delayed onset in CF+CFTR cell monolayers and required viable fungi and apical application." (PMID 37680748, 2023). "Whatever the mechanistic role of CFTR or other determinants in the onset of the innate immune response in CFLD, the ensuing chronic inflammation is responsible for the progression of lung damage apparently more than infection." (PMID 37895314, 2023). "To test whether microtubule dysregulation could influence bacterial clearance independently of CFTR function, we examine the levels of recovered CFU 3 days post infection." (PMID 37507487, 2023). "So far, neither animal nor human studies have clarified the impact of infection on concentrations and biodistribution of CFTR modulators." (PMID 36625583, 2023).
infection (continued). "Even if CFTR modulators do lessen ASM dysfunction in CF, ongoing inflammation and infection occur even with modulator therapy, which may also drive continuing AHR despite modulator use." (PMID 37568151, 2023). "Moreover, the IGFBP-6 expression was increased in both Wt- and F508del-CFTR CFBE and HNE cells under infection and inflammatory conditions." (PMID 35903151, 2022). "In contrast to downregulation of CFTR during SARS-CoV-WT infection, no reduction was observed in RNAseq expression of other ion transporters also involved in fluid clearance from airspaces, such as epithelial sodium channel (ENaC) and Na/K-ATPase." (PMID 35229638, 2022). "The higher bacterial counts and the faster degradation of epithelial integrity suggest that cells lacking functional CFTR were more vulnerable to infection than the control Calu-3 cells." (PMID 35563895, 2022). "Although infection was not studied, this model was able to evaluate the impacts of CFTR modulator therapies in in vitro airway cell cultures." (PMID 36081767, 2022). "Relative changes of gene expression in response to ASL manipulation followed or not by infection with the 105 CFU of ΔlasR strain for 16 h were normalized to uninfected CFTR-CTL in the CTL-ASL condition or CFTR-KD in the KD-ASL condition." (PMID 35563895, 2022). "HDR has succeeded in repairing F508del CFTR in primary human airway basal cell cultures and G551D CFTR in proliferating ferret airway basal cells, to which the components of the CRISPR system were delivered by either transfection or rAAV infection." (PMID 36304167, 2022). "Moreover, pre-incubation of F508del-CFTR cell with an anti-IGFBP-6 antibody to abolish its anti-inflammatory activity, increased pro-inflammatory cytokines expression under infection with LPS." (PMID 35903151, 2022). "To demonstrate the efficacy of a phage-PS/PA liposomes combination as a possible therapy to counteract Pa infection in patient with CF, we took advantage of a zebrafish CF model, lacking the CFTR function." (PMID 36188006, 2022). "To identify a potential cause for the enhanced susceptibility of Calu-3 cells lacking a functional CFTR to infection, we studied the expression of junctional protein complexes in the CFTR-CTL and CFTR-KD cells by Western blot." (PMID 35563895, 2022). "We report here that GD01-infected CFTR morphants rapidly succumb to intravenous infection, reflecting the hypersusceptibility of the young CF patient to this isolate, providing a first glimpse into CFTR-mediated host defences to GD01 infection." (PMID 34530447, 2021). "For each cell line tested, infection with lab strain PAO1 bacteria resulted in ~50% decrease in CFTR function relative to non-infected cells." (PMID 32092967, 2020). "Accumulating evidence indicates that loss-of-function of the Cystic Fibrosis Transmembrane Conductance Regulator (CFTR) is per se associated with a proinflammatory phenotype, even in the absence of infection." (PMID 32848748, 2020). "Decreased cytokine production was in contrast to a prior study of siRNA-silencing of CFTR in alveolar macrophages, although the authors only examined basal IL-8 production and not responses to infection." (PMID 32973772, 2020). "Infection with B. cenocepacia significantly reduced CFTR function in non-CF MDMs and further reduced CFTR function in CF MDMs." (PMID 33303916, 2020). "The treatment of F508del-CFTR cells with VX-809 does not decrease infection rate and does not potentiate 6K-F17 anti-infective activity." (PMID 32092967, 2020). "To determine if CFTR expression was also impacted by infections or treatments, we measured CFTR protein expression during infection with B. cenocepacia in the presence or absence of tezacaftor/ivacaftor, roscovitine, M3, or combinations." (PMID 33303916, 2020). "Only a combination of tezacaftor/ivacaftor and roscovitine significantly increased CFTR function in CF MDMs during infection compared to no treatment." (PMID 33303916, 2020).
infection (continued). "We also interrogated the effects of CFTR ablation on host immunity, inflammation, and infection independent of the overlapping infection and inflammation associated with the CF-lung microenvironment." (PMID 30759393, 2019). "By comparing monocytic- and epithelial-driven inflammation in CF and PCD, one is able to distinguish between inflammation due to recurrent infection, as is the case with both CF and NCFB, and inflammation that is downstream of CFTR/ENaC-mediated ionic disturbances, specific to CF." (PMID 31532390, 2019). "Of interest, in in vitro antimicrobial assays, MSCs with dysfunctional CFTR channel were not as efficient in handling infection as MSCs with fully active CFTR channel, suggesting the same scenario for CF patient’s MSCs as compared to healthy individual’s MSCs." (PMID 31861724, 2019). "The absence of normal CFTR expression on macrophages has been linked to increased inflammatory cytokine production, altered TLR4 trafficking and impaired resolution of infection and inflammation." (PMID 31262295, 2019). "Thanks to genetic and high-resolution imaging approaches, we report the direct stepwise dissection of Mabs infection in an animal lacking CFTR to elucidate the biological implication of CFTR in innate immunity to Mabs." (PMID 30759393, 2019). "Next, we examined the effect of impaired CFTR ion-channel-activity on PA01-GFP infection of RAW264.7 cells using CFTR172-inhibitor and found no significant change in phagocytosis." (PMID 25794013, 2015). "Compared to non-infected cells, scrambled infection neither affected CFTR mRNA (100 ± 55.3 vs. 83 ± 37.6, n = 3) nor protein expression (100 ± 14.8 vs. 103 ± 13.0 %, n = 3)." (PMID 26549988, 2015). "Dysfunction of CFTR in the platelets and neutrophils might contribute to abnormalities of lipoxin A4 and PAF in the circulation or airspace of lung during infection and inflammation." (PMID 24671173, 2014). "In contrast, F508del CFTR cells had the highest RSV titer on day 2 (4.6 ± 0.2 × 1010 PFU/mL), followed by a decrease in titer on days 4 and 6 post infection (Day 4: 1.1 ± 0.4 × 108 and Day 6: 8.2 ± 1.1 × 107 PFU/mL, respectively, p < 0.007 across all time points)." (PMID 24056672, 2013). "P. aeruginosa infection of wild-type epithelial cells was found to induce apoptosis, bacterial internalization, and caspase-3 and -6 activation, while infection of CFTR defective cells did not result in apoptosis." (PMID 21490807, 2011). "The anti-inflammatory IL-10, reported to be reduced in PA508 infection in CFTR knockout mice, was not altered in our present study." (PMID 21118573, 2010). "Thirty-five subjects were excluded for lack of infection data; 16 for lack of CFTR genotype information; 227 subjects for inability to classify CFTR mutations." (PMID 20932301, 2010). "Infection of CF HAE with PIVGFP alone showed that ciliated cells positive for GFP were negative for CFTR immunoreactivity (Figure 3Cii)." (PMID 19621064, 2009). "Because the released debris by cells undergoing necrosis initiate inflammatory response which is harmful in CF, it is important to understand why cells expressing mutant CFTR are more resistant to apoptosis than normal cells in the absence of infection." (PMID 20041182, 2009). "However, emerging data indicate that the relationship between CFTR modulation and infection dynamics is not straightforward." (PMID 41154689, 2025). "Additionally, has been demonstrated that CFTR dysfunction lowers the pH of the ASL, reducing antimicrobial peptide activity and increasing vulnerability to infections of well-known CF pathogens such as staphylococcus aureus (Sa), pseudomonas aeruginosa (Pa) and hemophilus influenzae (He)." (PMID 40227282, 2025). "CFTR modulators have been shown to be ineffective at eradicating chronic antimicrobial resistant P. aeruginosa and other CF pathogens, indicating that modulators alone are not suitable for managing infection." (PMID 39493847, 2024).
infection (continued). "It is therefore possible that while CF carriers may not need the support of modifier genes for their personal survival in normal times, they may not easily tolerate further losses of CFTR expression following infection by SARS-CoV-2 virus." (PMID 39043712, 2024). "Since AWL secretion depends on function of the alveolar epithelial cystic fibrosis transmembrane conductance regulator (CFTR) protein, an ion channel inhibited by IAV in vitro, we considered that IAV might promote alveolar SA infection by blocking defensive, CFTR-dependent AWL secretion." (PMID 37581936, 2023). "Indeed, CFTR KD cells infected with PAO1-expressing mCherry confirmed the close interaction between fibronectin and Pa at the luminal side of the CF epithelium 1 hour after infection." (PMID 36602863, 2023). "Furthermore, infection with native SARS-CoV-2 virus reduced CFTR mRNA expression, while a deletion mutant without an E protein PBM did not." (PMID 36625656, 2023). "Finally, the intestine is not affected as the airways by chronic inflammation and infection with CF pathogens or suffers organ damage and remodeling, which are factors that may significantly affect CFTR channel function independent of the basic molecular defect of CFTR mutations." (PMID 36013270, 2022). "Nevertheless, accumulating evidence indicates that the infectious and inflammatory CF lung environment augments the CFTR rescue by CFTR modulators, and thus complete suppression of inflammation and infection might not be desirable." (PMID 36553341, 2022). "The integrity of the CFTR-CTL cells was not affected by the PAO1 mutants after 24 h of infection." (PMID 35563895, 2022). "The following treatments do not have a goal of reducing or eliminating infection, however they have had a side effect of leading to reductions in infection rates and exacerbations in the case of CFTR modifiers or eliminating lung infection for a period of time in the case of lung transplants." (PMID 34576767, 2021). "Furthermore, greater expression of IL-1β, TNF, and IL-8 was still observed during infection with PAO1 than PA14 with or without the presence of CFTR(inh)-172." (PMID 33664232, 2021). "This intrinsic CFTR defect present in immune cells, together with abnormal signalling mechanisms in PWCF, may contribute to the exuberant inflammatory responses, prolonged inflammation, and delayed clearance of infection." (PMID 32887484, 2020). "Even with the advent of combination CFTR modulator therapy, which improves lung function but perhaps not infection and inflammation, continued investigation of initial neutrophil pathological activity is necessary to identify much-needed interventions that can address this problem." (PMID 32318073, 2020). "Persister strains of P. aeruginosa (PA287, PA380, PA214, PA330) isolated from the sputum of CF patients who have previously failed to eradicate infection after having undergone treatment with inhaled tobramycin, were grown on F508del-CFTR HBE cells chronically treated with VX-809." (PMID 32092967, 2020). "Our findings may be related to the small but significant decrease in the ability of CFTR KO macrophages to respond to a pro-inflammatory M1 stimulus, despite a higher proportion of M1 macrophages after CFTR KO in the absence of infection." (PMID 32973772, 2020). "Surprisingly, such exuberant neutrophil mobilization is not observed when CFTR-defective zebrafish are infected with CF pathogens, strongly implying tissue damage as the primary initiator in increasing inflammation rather than infection in CF." (PMID 32849617, 2020). "Interestingly, these findings are only observed with Mab and not with other mycobacteria; consequently, CFTR seems to have a specific role in the immune control of only Mab infections." (PMID 31766758, 2019).